RHO (rhodopsin)
Diseases named in the same sentence as RHO in open-access papers (continued):
Sharing a sentence is not in itself a finding about the gene and the disease.
cancer (continued). "Three GTPases, RAC, RHO, and Cdc42, play essential roles in coordinating many cellular functions during embryonic development, both in healthy cells and in disease conditions like cancers." (PMID 31027363, 2019). "Unlike KRAS and BRAF, mutations in RHO genes are extremely rare in tumours, but their expression and/or activity is frequently altered in a variety of human cancers." (PMID 21943101, 2011). "Targeted inactivation of RHO‐ROCK/MLCK‐MLC2 signaling in CT45A1High MSI‐H CRC cells may sensitize outer cancer cells to NK cell killing and enhance the accessibility of inner CT45A1Low cancer cells for NK cells, benefiting cancer immunotherapy in MSI‐H CRC patients." (PMID 39322998, 2025). "Altogether, this study provides a comprehensive map of RHO GTPase pathway alterations in cancer and identifies new oncogenic drivers, expression-based signatures, and therapeutic vulnerabilities that could guide future mechanistic and translational research in this area." (PMID 41480181, 2025). "Thus, albeit no drugs that target RHO GTPase pathway are currently in clinical trials for cancer therapy, the members of the RHO GTPase family are still considered interesting targets for the development of innovative cancer treatments due to the central role they play in many cellular processes." (PMID 31248017, 2019). "It is also known that small GTPases of the RHO/Rac family participate in TGFβ-induced EMT and cell motility in cancer, an effect that based on our results seems to be mediated in monocytes and macrophages in IPF, at least in part by MCEMP1." (PMID 38189137, 2024). "Cancer cell migration is an actomyosin-dependent process, consistent with the widespread effects of LPA on RHO GTPase signaling, actin and MLC2 with a major role for LPAR1." (PMID 37064875, 2023). "PRIMPOL expression was positively correlated with the levels of C4orf27, NPIPA1 (NPIP), RP4 (RHO) and SUGP2 (SFRS14) in pan-cancer." (PMID 37391787, 2023). "We will focus in particular on five members of the RHO GTPase family, including RHOA, RHOB, RHOC, RAC1, and CDC42, to illustrate the role of lncRNAs in cancer progression." (PMID 34771549, 2021). "Hence, comprehensive studies on different aspects of RHO GTPase structures, functions, and interactions as well as their mechanisms of regulation could help us to find new selective therapeutic strategies for cancer treatment." (PMID 34771549, 2021). "The DBC1 gene is located in human chromosome 9q32-33; The DBC1protein is a member of the RHO atypical family, which contains small GTP enzymes.DBC1 loses heterozygosity in many cancers and is a new genewith hypermethylation status in malignant tumor tissues." (PMID 29658966, 2018). "CT45A1, a vital driver of the RHO‐ROCK/MLCK‐MLC2 signaling, is found to enhance cancer cell resistance to natural killer (NK) cell killing and generate a protective cell‐in‐cell (CIC) structure in microsatellite instability‐high (MSI‐H) colorectal cancer (CRC) cells." (PMID 39322998, 2025). "These differentially expressed genes implicated several canonical pathways, including Molecular Mechanisms of Cancer, RHO GTPase cycle, Hepatic Fibrosis Signaling, Serotonin receptor Signaling and G-Protein Coupled receptor Signaling." (PMID 41510264, 2025). "Our observations provide support for the notion that the role of RHO‐ROCK signaling in establishing a tumor‐promoting microenvironment may be conserved across patients and potentially also different cancer types." (PMID 38979935, 2024). "More specifically, the DEGs involved in RAS/RAF/MAPK, PI3K/AKT, WNT, NOTCH, TGF-β, integrin, EMT process, focal adhesion, RHO GTPase-related pathway or microtubule cytoskeleton regulation are upregulated when PRC1 expression is above median, as confirmed for most cancers." (PMID 37563591, 2023). "This revealed RHO, RAC and PDPK14,5,20, well established as key regulators of the actin cytoskeleton (Rho and Rac) and proliferation (PDPK1), which are often mis-regulated in cancer." (PMID 32127582, 2020).
cancer (continued). "Moreover, many of them (such as MAPK, RHO, NOTCH, PDGF, RAS, JUN, ARF, PIK3) also belong to other cancer-related pathways." (PMID 22824167, 2012). "RHO, RAC1, and CDC42 are all members of the RHO GTPase family and are involved in the regulation of cytoskeleton, cell growth, and cell cycle, which may be effective targets against malignant tumor metastasis." (PMID 37202394, 2023). "Moreover, RHO GTPase signaling controls MMPs levels and cell polarity maintenance, functions that need to be altered to allow cancer cells to proliferate without control and invade the extra-cellular matrix." (PMID 35337349, 2022). "Given that RHO GTPases participate in various cellular functions, there is no doubt that they are connected with almost every stage of cancer development and progression, such as the dysregulation of cell proliferation, angiogenesis, resistance to apoptosis, tissue invasion, and metastasis." (PMID 36348464, 2022). "Overexpression of CT45A1 increased cancer cell resistance to NK cell killing via the RHO‐ROCK/MLCK‐MLC2 signaling axis and promoted outer cell fate in homotypic CIC structures without affecting cancer cell motility in MSI‐H CRC cell lines." (PMID 39322998, 2025). "Last, the lack of knowledge about the role of each GTPase in human cancer, i.e., the recent description of a tumor suppressor activity for RHOA in AITL, PTCL, and Burkitt’s lymphoma, has raised concerns about a strategy of inhibition of RHO GTPase signaling." (PMID 31248017, 2019).
tumor (52 papers, 2010 to 2026). "Inhibitors of RB1-deficiency or MET plus RHO-signaling cooperate to block cell migration and drive tumor cell-death." (PMID 37463901, 2023). "In hematological malignancies, deregulation of the RHO GTPase signaling network has been reported, mainly related to constitutive activation of upstream signaling and implicated to tumor dissemination and invasion." (PMID 31248017, 2019). "Given the activating functions of the RHO GEFs and RHO effectors in the RHO GTPase network signaling, they are typically associated with pro-tumorigenic functions in tumors, whereas RHO GAPs, that are negative regulators, are frequently considered as tumor suppressors." (PMID 31248017, 2019). "GSEA analysis further corroborated the GO/KEGG enrichment results, while enrichment in RHO gtpases also indicated the involvement of PLK1 in multiple processes in tumour growth, including mitosis, cell death, immunosuppression, and drug resistance." (PMID 37744268, 2023). "Genomic alterations in DLC1 contribute to drug sensitivity and confer growth advantage upon activation of RHO-ROCK signalling, rendering tumour cells more susceptible to ROCK-inhibitors (e.g., Y-27632)." (PMID 35963849, 2022). "The other gene sets associated with tumor ranked in top 30 gene sets included hypoxia, tumor environment, NF-kB targets, RHO pathway, EGF response and epithelial differentiation." (PMID 33753999, 2021). "Initially (within 16 hours), CD97-mediated interaction with platelets induces release of platelet LPA and activates RHO in tumor cells, promoting tumor cell invasiveness." (PMID 33042789, 2020). "The experimental approach used here can be also utilized to pinpoint therapeutically interesting RHO signaling elements in any tumor type with a more rational and patient-oriented aprioristic basis." (PMID 32963234, 2020). "DLC1 has been well characterized as a tumor suppressor protein, suppressing tumor growth and metastasis through its RhoGAP domain to inhibit RHO signaling activity." (PMID 29084958, 2017). "Cellular transformation by oncogenic RAS requires the RHO guanine exchange factor ARHGEF2 (also known as GEF-H1) for tumor growth and survival." (PMID 27835861, 2017). "Given that RHO‐ROCK signaling promotes tumor progression in cSCC, we therefore wondered whether CRELD2 has a role in cSCCs exhibiting ROCK activation and if so, whether this was associated with enhanced fibroblast infiltration in human patients." (PMID 38979935, 2024). "In this regard, inhibitors acting on the RHO/ROCK-mediated pathway are becoming a promising therapeutic approach for vascular endothelial growth factor (VEGF)-induced angiogenesis in the context of tumor progression and invasion." (PMID 34124035, 2021). "Regulation of expression of RHO GDIs has been reported in different studies, although the situation is more complex because these changes depend on the tumor type and correlate differently with the tumor phenotype." (PMID 31248017, 2019). "Finally, as SEMA4D is a novel prognostic indicator in Group 3 and Group 4 patients, is associated with a decrease in self‐renewal, and growth and is an upstream regulator of RHO activity, we evaluated the effect of this candidate gene on tumor growth in vivo." (PMID 29377567, 2018). "Cytoskeleton-regulating proteins, including rhodopsin (RHO), CDC42 and ras-related C3 botulinum toxin substrate 1 RAC1 (RAC1), which are members of the RAS family due to high similarity, are implicated in tumor metastasis." (PMID 28179017, 2017). "Thus, both gain- and loss-of-function mutations in specific RHO GTPase pathway genes have been detected in human tumors, with some RHO proteins and their signaling components unexpectedly acting as tumor suppressors in certain contexts (e.g., the RHO GEFs VAV1 and TIAM1)." (PMID 41480181, 2025).
tumor (continued). "Despite this relevant difference, VAV proteins share a very similar structure and can exhibit overlapping functions, suggesting that VAV2 and VAV3 might play tumor suppressor roles similar to those carried out by VAV1 beyond the long-held signaling archetype for RHO GEFs." (PMID 34571765, 2021). "In the adult retina, a bistable feedback loop of the growth regulator melted and the tumor suppressor warts acts to specify Rh5 versus Rh6 cell fate, respectively, while in the larva, Sens, Sal, Svp and Otd control Rh5 versus Rh6 identity whereas Hazy has been shown to maintain Rhodopsin expression." (PMID 24385925, 2013). "Thus, through RHO and RAS/MAPK activities, this signaling pathway has been implicated in the maintenance of epithelial tissue architectures and is therefore thought to act as a tumor suppressor." (PMID 21124932, 2010). "Both showed interaction with multiple candidate GTPases of the RAS, RHO, and ARF subfamilies in our screen, predominantly with tumor suppressor-class RAS subfamily GTPases." (PMID 39009833, 2024). "RHO‐ROCK signaling, and consequent tension within the cellular actomyosin cytoskeleton, regulates a paracrine signaling cascade that establishes a tumor‐promoting microenvironment." (PMID 38979935, 2024). "For example, proteins connected to the hemostasis (e.g., Fibrinogens), and proteins involved in the RHO protein signal transduction (e.g., Apoliproteins, CO1A2) showed lower expression levels only in SqCC tissue compared to tumor-adjacent tissue." (PMID 35681609, 2022). "In the case of the RHO GTPase-related lncRNAs, results showed that the subcutaneous delivery of MALAT1 phosphorothioate-modified ASO successfully suppressed primary tumor differentiation." (PMID 34771549, 2021). "In solid tumors, RHO GTPases are frequently activated by upstream tyrosine kinase receptors, such as ERBB2 or MET, and contribute to tumor progression and metastasis." (PMID 31248017, 2019). "A key role for RHO-ROCK signaling has been delineated in the tissue and tumor microenvironments, to complement its well-established function in cell migration and adhesion." (PMID 30356678, 2018). "This isoform is functional GAP protein and tumor suppressor and targeting of its expression results in the increase of DLC1 related cell processes: RHO activation and cell migration." (PMID 27614886, 2016). "Vandetanib plays an anti-tumor role by inhibiting VEGF/MAPK and RET/RHO/JNK signaling pathways." (PMID 36544713, 2022). "Therefore, the contribution of ZFAS1/miR-3924 in tumor metastasis via the RHOA/ROCK2 pathway was reported, confirming its potential regulatory effect on RHO GTPase members." (PMID 34771549, 2021). "In this article, we also found that BCAP31 may participate in the regulation of tumor cell migration and invasion through GTP metabolism and RHO signal pathway." (PMID 32582765, 2020). "Therefore, the CamK-II/RHO/ROCK/MLC2 pathway transduces the 12(S)-HETE signal in CAFs, leading to retraction and opening the gate for tumour invasion in vitro." (PMID 28013338, 2017). "Finally, the discovery of tumor suppressor activities of RHO GEFs, in particular, those related to VAV proteins, raises a new scenario for the development of approaches to inhibit the RHO GEF activities." (PMID 34571765, 2021). "Pharmacological inhibition of downstream factors such as Arp2/3, a major regulator of actin assembly and migration, may block RHO signaling regardless of the upstream oncogenic alterations or signals from the tumor microenvironment that may induce the pathway, and restrict metastatic dissemination." (PMID 37463901, 2023).
tumor (continued). "Interestingly, RHO proteins can interact with a considerable number of targets, directly affecting cellular contractility, motility, and migration, and (actin) cytoskeleton rearrangement, which is in line with CD97-regulated cellular functions in normal and tumor cells." (PMID 35563846, 2022). "Since activated RHO GTPases in fibroblasts reportedly promote SCC invasion, upregulation of the cell–extracellular matrix interaction pathway and RHO GTPase-mediated pathways may regulate ECM deposition and remodeling, resulting in tumor cell invasion and metastasis." (PMID 33799788, 2021).
retinopathy (22 papers, 2007 to 2025). "Compounding these issues is the extensive mutation heterogeneity in rhodopsin-associated retinopathies." (PMID 41009537, 2025). "This review aims to summarize the progress in studies on the mechanism and therapy for retinal disorders related to rhodopsin mutations, including RP and CSNB." (PMID 37077319, 2023). "The expression of many of retinopathy variants can be partially restored by analogs of rhodopsin’s native 11-cis-retinal cofactor and/or other small molecules that bind and stabilize the opsin apoprotein." (PMID 35850308, 2022). "In this work, we utilize DMS to characterize the proteostatic effects of 123 retinopathy-linked rhodopsin variants in HEK293T cells and measure their response to the investigational corrector 9-cis-retinal." (PMID 35850308, 2022). "Over the past few decades the fly photoreceptor has been used as a powerful model system to study human retinopathies, including those linked to defects in Rhodopsin trafficking." (PMID 29651238, 2018). "In mice, the availability of RPE65 was shown to modulate retinal susceptibility to light damage; higher concentrations causing a more severe retinopathy (due to a faster regeneration and, thus, increased availability of rhodopsin)." (PMID 27355622, 2016). "This disease is unique, to date, among canine inherited retinopathies in that it is inherited as an autosomal dominant disease, and is caused by a single non-synonymous C → G transversion at nucleotide 11 of rhodopsin (RHO) that changes Thr-4 to Arg (T4R)." (PMID 26401320, 2014). "Given that over 150 distinct rhodopsin mutations have been associated with inherited retinopathies, further investigation is warranted to assess whether this mechanism extends across the broader spectrum of RHO-RP." (PMID 41056359, 2025). "Together, these results identify a subset of “correctable” retinopathy variants and imply that proteostatic responses may be tied to differences in opsin/rhodopsin stability." (PMID 35850308, 2022). "We observed significantly reduced levels of usherin p.(Cys771Phe) at the zebrafish photoreceptor periciliary membrane and increased levels of aberrantly localized rhodopsin, which was previously shown to be a hallmark of ush2a-associated retinopathy in a zebrafish knock-out model." (PMID 35672333, 2022). "Understanding the molecular basis of these observations may therefore help to inform efforts to develop efficacious correctors for retinopathies caused by rhodopsin misfolding." (PMID 34756884, 2021). "Such information could be of clinical value in the diagnosis, longitudinal monitoring of disease progression and efficacy evaluation of treatments in retinal disorders with altered rhodopsin expression in photoreceptors or actual photoreceptor loss." (PMID 26358529, 2015). "Thirdly, recent studies in which crb was mutagenized at conserved residues located in the extracellular domain that are associated with human retinopathies, have revealed a complex pattern of trafficking for Crb, and how it might in turn influence Rhodopsin trafficking, including endocytosis." (PMID 29651238, 2018). "Hence, the authors state that the heterozygous RHO E150K-associated retinopathy should rather be classified as slowly progressing adRP instead of pure arRP and encourage all human patients carrying this mutation heterozygously to have a follow-up monitoring of their retinal function." (PMID 26887858, 2016). "Rhodopsin (Rho) trafficking is essential for rod homeostasis, as its mislocalization precedes rod cell death in inherited retinal disorders such as retinitis pigmentosa." (PMID 41185951, 2025). "This review also integrates and updates the information on pharmacological intervention, optogenetics, gene therapy and gene editing, and stem cell therapy for rhodopsin-related retinal disorders that were reviewed previously." (PMID 37077319, 2023).
retinopathy (continued). "Mutations in NRL are associated with retinopathies; many of these are suggested to change phosphorylation status and alter NRL-mediated transactivation of rhodopsin promoter." (PMID 17653056, 2007). "Further, mice with a single rhodopsin gene only have a mild retinopathy." (PMID 40820815, 2025). "Alternatively, focus on discovering of non-retinoid small molecules beneficial in retinopathies associated with mutations in rhodopsin is currently a fast-growing pharmacological field." (PMID 31835521, 2019). "Furthermore, scotopic ERGs were more attenuated than photopic ones, findings in accord with previous studies that showed that LIR is a rhodopsin-mediated retinopathy." (PMID 31167447, 2019). "As inhibition of MAPK signaling pathways decreases NRL-mediated transactivation of rhodopsin promoter, we propose that phosphorylation changes associated with NRL mutations perturb gene expression in rods, leading to photoreceptor degeneration in retinopathies." (PMID 17653056, 2007). "Three months after the induction of diabetes, the DM rats showed changes indicative of retinopathy such as decrease in the thickness of retina, increase in the expression of VEGF and HIF-1α and decrease in the expression of rhodopsin." (PMID 35439275, 2022).